HEBP2 (heme binding protein 2)
Description:
Can promote mitochondrial permeability transition and facilitate necrotic cell death under different types of stress conditions.
Synonyms: PP23; C6orf34; SOUL; C6ORF34B
Tractability: Small molecule: it has a binding pocket of medium quality. Antibody: its Gene Ontology location is reachable by antibodies, with high confidence. PROTAC: ubiquitination databases record sites on it; its protein half-life has been measured.
Gene: Protein-coding gene on chromosome 6 (138,403,531 to 138,422,197, forward strand). Ensembl gene ENSG00000051620.
Subcellular location: Cytoplasm; Mitochondrion
Pathways (Reactome):
Immune System: Neutrophil degranulation
Gene Ontology:
Molecular function: protein binding; heme binding
Cellular component: cytoplasm; extracellular exosome; mitochondrion; azurophil granule lumen; extracellular region
Genetic constraint (gnomAD): Loss-of-function variants: 27 observed, 23.63 expected, observed/expected ratio (o/e) 1.14, 90% interval 0.84 to 1.57. The upper end of that interval is the gene's LOEUF score, 1.57, which puts it in group 6 of 6, group 1 being the genes least tolerant of losing a copy. Missense variants: 245 observed, 241.35 expected, observed/expected ratio (o/e) 1.02, 90% interval 0.91 to 1.13. Synonymous variants: 99 observed, 88.34 expected, observed/expected ratio (o/e) 1.12, 90% interval 0.95 to 1.32.
Homologues: Orthologues: chimpanzee HEBP2 (99% identical), macaque HEBP2 (97% identical), mouse Hebp2 (84% identical), dog HEBP2 (82% identical), rat Hebp2 (81% identical), guinea pig HEBP2 (72% identical), rabbit HEBP2 (63% identical), zebrafish hebp2 (43% identical). Paralogues in human: HEBP1 (23% identical).
Diseases named in the same sentence as HEBP2 in open-access papers:
HEBP2 is named in the same sentence as 15 diseases in open-access papers, as found by Europe PMC text mining. Sharing a sentence is not in itself a finding about the gene and the disease. The quoted sentences say what the papers report.
lung carcinoma (2 papers, 2019 to 2024). "HEBP2 upregulation is a biomarker of poor prognosis in breast and lung cancer, likely a result of dysregulated microtubule dynamics during mitosis." (PMID 38398114, 2024).
porphyria (2 papers, 2015 to 2023). Porphyria is a group of diseases in which substances called porphyrins build up, negatively affecting the skin or nervous system. "Therefore, our results also indicate the attenuation of porphyria in Amulet due to increase of heme-binding protein 2, delta-aminolevulinic acid dehydratase, and GSTs." (PMID 26175745, 2015). "Although HEBP2 and SLC25A37 have been described to be involved in different diseases such as cancer, anemia, porphyria, or depression, we focused on TFAM for further studies due to its widely observed implication in different neurodegenerative disorders, PD being among them." (PMID 36674978, 2023).
breast tumors (1 paper, 2012). "Additionally, a number of prosurvival (BCL2, PPEF2) and proapoptosis (BID, HEBP2, and PKNOX1) genes were up- and downregulated, respectively, in bone metastases compared with primary breast tumors." (PMID 23174366, 2012).
insomnia (1 paper, 2020). A sleep disorder characterized by difficulty in falling asleep and/or remaining asleep. "The insomnia-associated gene of HEBP2 has shared protein domains with the insomnia-associated gene of TEX264, and TEX264 show evidence of co-expression with DALRD3." (PMID 32830860, 2020). "Furthermore, by conducting a DGE analysis, we found that three genes of DALRD3 (P=5.0 × 10−5), LDHA (P=0.044), and HEBP2 (P=0.032) showed significantly down-regulated expression in insomnia brain samples compared with controls." (PMID 32830860, 2020). "In conclusion, the current comprehensive study provides multiple lines of evidence for supporting DALRD3, LDHA, HEBP2, TEX264, and FGFR3 as insomnia-associated genes whose abnormal expression level may convey risk to insomnia." (PMID 32830860, 2020).
malignant glioma (1 paper, 2023). A grade III or grade IV glioma arising from the central nervous system. "By performing differential expression analysis on our malignant glioma samples, we identified four DEGs, CD74, HES1, CALD1, and HEBP2, significantly upregulated in the AQP4 high expression group." (PMID 36599974, 2023).
neuroblastoma (1 paper, 2024). Neuroblastoma (NB) is the most common solid, extracranial childhood tumor. "The upregulation of genes BSG/CD147, CCDC125, GABRB3, GNB2L1/RACK1, HAPLN4, HEBP2, and HSD17B12 is associated with poor neuroblastoma prognosis and low EFS." (PMID 38398114, 2024).
Obesity (1 paper, 2021). Accumulation of substantial excess body fat. "On the other hand, monocytes from mothers with obesity (n = 3/time point) exhibited suppression of genes involved in interferon signaling (STAT1, GBP5, PSMB8) and response to reactive oxygen species (STRBP, HEBP2, TRAP1, TRPA1) (p value <0.001) with gestational age." (PMID 34195568, 2021).
cancer (4 papers, 2018 to 2024). A tumor composed of atypical neoplastic, often pleomorphic cells that invade other tissues. "Of these, BSG/CD147, HEBP2, HSD17B12, and GNB2L1/RACK1 have well characterised functions in cancer and cell survival." (PMID 38398114, 2024).
tumor (2 papers, 2023). "As for HEBP2, there is not enough evidence showing its correlation with tumor cells, but it is believed that its related pathways are innate immune system." (PMID 36599974, 2023). "Concomitant with the overexpression of AQP4, genes related to the immune system were also over-expressed, such as CD74, HES1, CALD1, and HEBP2, indicating AQP4 may relate to immune factors of tumor progression." (PMID 36599974, 2023).
HEBP2 also shares sentences with these, for which no sentence is quoted: anemia (1 paper); depression (1); esophageal cancer (1); pancreas adenocarcinoma (1); rectal cancer (1); rectal tumor (1).